ENSG00000202335
Synonyms: LOC124903099
Gene: Small nucleolar RNA gene on chromosome 12 (110,496,352 to 110,496,421, reverse strand). Ensembl gene ENSG00000202335.
Gene Ontology:
Biological process: RNA processing
Cellular component: nucleolus
Homologues: Paralogues in human: SNORD50B (93% identical).